CD47 (CD47 molecule)
Diseases named in the same sentence as CD47 in open-access papers (continued):
Sharing a sentence is not in itself a finding about the gene and the disease.
cancer (continued). "CD47 is an emerging target for cancer immune checkpoint therapy by its functioning as a “Don’t eat me” signal to avoid the phagocytosis by macrophages." (PMID 34805154, 2021). "The therapeutic targeting of the innate immune checkpoint CD47-SIRPα has the ability to enhance antitumor effects of myeloid cells, especially in the presence of cancer-opsonizing antibodies." (PMID 34503071, 2021). "RRx-001 is a molecule that targets and downregulates both CD47 on cancer cells and SIRPα on macrophages." (PMID 33741032, 2021). "Magrolimab is a first-in-class mAb against CD47 that interferes with the CD47-SIRPα axis and inhibits the "don't eat me" signal used by cancer cells to avoid being ingested by macrophages." (PMID 33879198, 2021). "In this way, cancer cells exploit the “don't eat me signal” provided by CD47 and avoid a cornerstone component of antitumor immune response." (PMID 34195295, 2021). "On the other hand, targeting myeloid immune checkpoints, such as CD47-SIPRα, provide the opportunity to enhance antitumor effects of myeloid cells, including that of neutrophils, especially in the presence of cancer-opsonizing antibodies." (PMID 34503071, 2021). "Cancer cells express CD47 to protect cells from phagocytosis by binding and activating the receptor SIRPα on macrophages to inhibit macrophage phagocytosis." (PMID 34717710, 2021). "The expression of CD47 on cancer cells can inhibit myeloid cell-mediated clearance in a manner similar to the inhibition of T cell activity by tumors via PD-1/PD-L1 interaction." (PMID 34717705, 2021). "CD47 plays vital roles in cell functional behavior and immune homeostasis relating to cancer prognosis." (PMID 34966389, 2021). "As a self‐protection protein, CD47 plays a pivotal role in enabling cancer cells to evade immune elimination." (PMID 33449453, 2021). "CD47 antagonists enhance not only phagocytic uptake of cancer cells by macrophages but also antigen presentation, which further triggers cross-priming of T cells." (PMID 33919517, 2021). "Accumulating data from laboratory and clinical studies have not only revealed highly expressed CD47 in many types of cancers, but also provided encouraging data for the novel therapeutic strategy by targeting CD47." (PMID 33765961, 2021). "Previously, miR-222 was reported to be up-regulated in response to IR; moreover, overexpression of miR-222 enhanced radiosensitivity by targeting CD47-ERK pathway in cancer cells." (PMID 33942856, 2021). "CD47, known as the “don’t eat me” signal, is the phagocytosis checkpoint as a new target for cancer immunotherapy." (PMID 34589427, 2021). "SIRPα-CD47 axis blockade enhances cancer cell clearance by phagocytes, which in turn promotes antigen cross-presentation by APCs resulting in enhanced T cell priming." (PMID 34512146, 2021). "Clinical implications of CD47 overexpression were also studied in various cancer types with the majority showing an inverse relationship between CD47 overexpression and clinical outcomes." (PMID 34944850, 2021). "Inhibition of CD47–SIRPα signaling in itself is a prominent therapeutic avenue that promotes phagocytosis of cancer cells by innate immune cells." (PMID 35052746, 2021). "Some researchers have synthesized responsive exosomes nano-bioconjugates for cancer therapy, which coupled the azide-modified exosomes derived from M1 with dibenzocyclooctyne-modified antibodies of CD47 and SIRPα." (PMID 34625124, 2021). "Blocking the CD47-SIRPα checkpoint as an anticancer therapy is under intense investigation since CD47 is overexpressed on AML as well as on various other cancer types." (PMID 34579739, 2021). "Currently, 10 CD47 antibodies and four SIRPα fusion proteins are being evaluated for clinical efficacy in various type of cancer." (PMID 33449453, 2021). "CD47, a cell surface glycoprotein, is a novel checkpoint commonly express on the surface of cancer cells." (PMID 33867849, 2021).
cancer (continued). "Our research provides a promising candidate for cancer immunotherapy, bridging the innate and adaptive immunity by a CD47/SIRPα and TIGIT/PVR blockade." (PMID 34068552, 2021). "Under hypoxic conditions, HIF-1 induces CD47, overexpressed in many cancers who can bind with SIRPα (signal regulatory protein alpha), an inhibitory receptor which is mostly located on macrophages." (PMID 34595122, 2021). "In short, the CD47-SIRPα signaling pathway has a great therapeutic potential, and CD47 has become another highly competitive target after PD-1/PD-L1 in cancer immunotherapy." (PMID 34717705, 2021). "Especially, combined CD47/SIRPα with PD-1/PD-L1 checkpoints blockade will be preferred to inhibit cancer cell immune evasion." (PMID 34512146, 2021). "CD47-targeted bismuth selenide (Bi2Se3) NPs have also been employed to deplete TAMs in tumors and to promote macrophage-mediated phagocytosis of cancer cells." (PMID 34575416, 2021). "Various cancer types including solid tumors as well as hematological malignancies have shown to harness the SIRPα/CD47 pathway to evade immune surveillance by overexpressing CD47." (PMID 34276685, 2021). "Firstly, we used oncomine, GEPIA and TIMER databases to investigate CD47 expression at pan-cancer level." (PMID 34966389, 2021). "A further explanation for the differential binding of CD47 mAbs to cancer versus normal cells lies in potential differences in surface mobility of CD47 on different cell types or different densities or distribution of CD47 in the lipid rafts." (PMID 34717705, 2021). "Strategies aiming at blocking the TSP-1/CD47 axis are currently in the limelight of innovations for the management of cancer." (PMID 34638503, 2021). "In recent years, accumulating data suggest that the CD47-SIRPα axis is a key immune checkpoint in different cancers including hematological malignancies, similar to that of the PD-1/PD-L1 checkpoint for solid tumors." (PMID 34717705, 2021). "In several instances, research has barely progressed past pre-clinical animal models of disease and early phase 1 clinical trials, while for cancers, anti-CD47 therapy has emerged from phase 2 clinical trials in humans as a crucial adjuvant therapeutic agent." (PMID 33920030, 2021). "Anti-CD47 antibodies block the binding of CD47 to SIRPα, and thus increase phagocytosis of cancer cells, representing an efficient strategy of TAM reprogramming." (PMID 33968014, 2021). "A further modification of Bi2Se3 NPs consisted of polyethylene glycol (PEG) functionalization and an anti-CD47 antibody (Ab) coating to target cancer cells." (PMID 34575416, 2021). "The crosstalk between the cancer cell CD47 and the macrophage signal-regulatory protein alpha (SIRPα) has been designated as the innate immune checkpoint." (PMID 34575416, 2021). "The binding of CD47-SIRPα transmits a “don’t eat me” signal, which can prevent cancer cells from immune clearance." (PMID 34595122, 2021). "Recent breakthroughs have highlighted phagocytosis checkpoint axes which can be targeted to induce the anti-cancer functions of macrophages, such as the CD47-SIRPα phagocytosis axis, PD1-PDL1 axis, MHC I–LILRB1 axis, and CD24–Siglec-10 axis." (PMID 33790906, 2021). "Several microRNAs including miR340 and miR128 inversely correlate with CD47 expression in PDAC cancer cells and negatively regulate its expression." (PMID 34201127, 2021). "Since macrophages exert immune surveillance against cancers, cancer cells overexpress CD47 to defend themselves against phagocytosis." (PMID 34944878, 2021). "“Don’t eat me signals” are proteins that are upregulated on cancer cells and help them avoid the immune response, among which the best studied are CD47, PD-L1 but also CD24 and MHC-I." (PMID 33919517, 2021). "The interaction between cluster of differentiation 47 (CD47) on cancer cells and signal regulatory protein alpha (SIRPα) on immune cells, such as macrophages and dendritic cells, generates a “don’t eat me” signal." (PMID 34944850, 2021).
cancer (continued). "Its extracellular domain (ECD) is a cell surface marker of self that binds SIRPα and inhibits macrophage phagocytosis, and cancer immuno-therapy approaches in clinical trials are focused on blocking CD47/SIRPα interaction." (PMID 34471125, 2021). "Targeting CD47-SIRPα axis has become a potential therapeutic mechanism in various preclinical models by stimulating the phagocytosis of cancer cells in vitro and in vivo." (PMID 34717710, 2021). "In this study, it shows that the formation of pyroglutamate on CD47 enhances the binding of SIRPα to CD47, consequently, inhibits cancer cell clearance by phagocytes." (PMID 34512146, 2021). "The phagocytic functions of these cells have been shown to be modulated through multiple pathways, including the CD47-SIRPα axis, which is manipulated by cancer cells for immune evasion." (PMID 33748077, 2021). "In this article, we review the role of CD47/SIRPα axis in cancer, and summarize the literature on the efficacy and safety of therapeutics targeting CD47 or SIRPα." (PMID 34944850, 2021). "The PD-L1 and CD47 antibody simultaneous blocking “don’t find me” and “don’t eat me” signal mediated more effective anti-cancer immunity in a mouse model compared with single antibody treatment." (PMID 34439285, 2021). "Based on these observations, targeting CD47 is considered a novel immunotherapeutic strategy for several human cancers that are refractory to T-cell immune checkpoint inhibitors." (PMID 33799989, 2021). "Preclinical study showed that SRF231 can bind with high affinity to CD47 and kill cancer cells in vitro with a strong antitumor activity." (PMID 34717705, 2021). "IMC-002 showed optimal affinity to CD47 ligand in multiple types of CD47-expressing cancer cell lines in a preclinical study." (PMID 34584838, 2021). "Targeting CD47 respectively SIRPα and therefore targeting the innate immune system provides a novel approach in cancer therapy." (PMID 34276685, 2021). "Given the huge potential of anti-CD47 bsAbs, there is ongoing interest in expanding this field in cancer immunotherapy and several bsAbs targeting CD47 have entered into clinical trials." (PMID 34305918, 2021). "Cancer cells, on the other hand, upregulate the expression of the “don’t-eat-me” molecule CD47 on their surface to avoid phagocytic uptake by APCs despite high surface CRT." (PMID 34069922, 2021). "Much progress has been made in targeting CD47 for cancer immunotherapy in solid tumors (ST) and hematological malignancies." (PMID 34717705, 2021). "Agents that inhibit CD47–SIRPA signaling can induce the phagocytosis of cancer cells by macrophages, resulting in growth inhibition and regression in xenograft models." (PMID 33799989, 2021). "CD47 is the best known “don’t eat me” signal, and mediates resistance to cancer cell phagocytosis by macrophages in efferocytosis and ADCP." (PMID 34638388, 2021). "CD47 is overexpressed on the cell surface by a variety of malignant cells; its blockade with monoclonal antibodies allows phagocytosis of cancer cells and leads to tumor rejection and development of antitumor immunity." (PMID 34561422, 2021). "A novel anti‐CD47 antibody, c4D10, showed effective therapeutic potential through inducing the eradication of human cancer cells (A) and demonstrated good tolerance in in vitro and in vivo toxicity studies (B)." (PMID 33449453, 2021). "Antibodies or other blocking agents, targeting the CD47‐SIRPα axis and blocking the cross‐talk between macrophages and cancer cells, will induce dramatic and durable antitumour immunity by bridging innate and adaptive immune responses." (PMID 33449453, 2021). "The binding of CD47 expressed on cancer cells to SIRPα expressed on macrophages inhibits phagosome formation preventing the engulfment of cancer cells." (PMID 33919517, 2021). "Elevated CD47 expression on some cancer cells protects tumors from innate immune surveillance and limits adaptive antitumor immunity via inhibitory SIRPα signaling in antigen-presenting cells." (PMID 34717705, 2021).
cancer (continued). "Inhibition of CD47 signaling by monoclonal antibodies (mAb) helps macrophages to eliminate cancer cells and reduces tumor growth, leading to a potential curative approach when tumors are treated in their initiation phase." (PMID 34572776, 2021). "Through the stimulation of IL-2, NK cells upregulate the expression of SIRPα, which interacts with the inhibitory ligand CD47 expressed on cancer cells, delivering an inhibitory signal to NK cells." (PMID 34439285, 2021). "To date, most efforts focused on targeting CD47 by using blocking antibodies, especially in the purpose of disrupting CD47/SIRPα signaling to promote cancer-cell phagocytosis." (PMID 34638503, 2021). "Cancer cells can be recognized through anti-CD47 therapy, and cancer clearance function can be increased through metabolic reprogramming." (PMID 33937269, 2021). "CD47 protects healthy cells from macrophage attack by binding to signal regulatory protein α (SIRPα), while its upregulation in cancer prevents immune clearance." (PMID 34729396, 2021). "As CD47 also promotes the proliferation of cancer cells via the PI3K/AKT pathway, the CD47 signaling pathway is considered an important mechanism of therapy resistance." (PMID 34094963, 2021). "constructed a macromolecular Gln analogue, Gln-functionalized branched polyethylenimine (GPI), as a carrier to deliver anti-CD47 siRNA to block the CD47 “don’t eat me” signal on cancer cells." (PMID 35223460, 2021). "Highly expressed CD47 levels are present in multiple types of cancers including solid tumors and hematologic malignancies, which is major regulated by some transcription factors such as NFκB, Myc, HIF-1 and NRF-1." (PMID 34512146, 2021). "In multiple types of cancer cells and solid tumor tissues, highly expressed CD47 protein level has been observed, which is triggered by some transcription factors including NFκB, Myc, and HIF." (PMID 34512146, 2021). "CD47 is a cell surface receptor that regulates macrophages from attacking healthy cells and is known to be overexpressed in cancers; B2M is a marker on MHC class 1 molecules; and EPCAM is a transmembrane receptor on epithelial cells that aids cell adhesion." (PMID 33690223, 2021). "Several humanized CD47 antibodies and SIRPα decoys have entered clinical trials as cancer therapeutics." (PMID 33925464, 2021). "This is particularly interesting in the context of anti-CD47 therapy, where macrophages are activated to phagocytose CD47-expressing cancer cells." (PMID 33391977, 2021). "The regulation of the anti-phagocytic signal CD47 is crucially important to surveillance against cancer cells." (PMID 34093795, 2021). "Overexpression of CD47 enables cancer cells to escape immune surveillance and destruction by phagocytes." (PMID 33449453, 2021). "High expression of CD47 would help cancer cells evade macrophage-mediated phagocytosis and is associated with growth and progression of many types of cancers." (PMID 33765961, 2021). "Increasing evidence suggests that SIRPα-CD47 checkpoint blockade enhances the efficacy of cancer immunotherapy." (PMID 34512146, 2021). "Many human cancer cells have the eat-me signal calreticulin on the surface (possibly due to ER stress, or possibly a tumour suppressor mechanism), but overexpress the don’t-eat-me signal CD47 to prevent host phagocytes from phagocytosing the cancer cells." (PMID 34177884, 2021). "As expected, Miap410 Ab treatments caused an initial drop in the erythrocyte count that returned to normal within 3 weeks, which is similar to the situation reported in human patients who had received CD47 Ab as a treatment for cancer." (PMID 34591795, 2021).
cancer (continued). "Third, radiation downregulates CD47 expression on the cell surface and enhances the cancer cells’ uptake and antigen presentation." (PMID 34579759, 2021). "CD47 is ubiquitously expressed on several cell types but is over expressed on the cancer cell surface, it engages with SIRPα expressed on phagocytes to deliver a ‘don't eat me’ signal which prevents cell clearance through phagocytosis." (PMID 34688033, 2021). "Immunocytochemistry showed a significant ratio of the KAIMRC2 cells’ expressing key breast epithelial and cancer stem cells (CSCs) markers, including CD47, CD133, CD49f, CD44, and ALDH-1A1." (PMID 34073849, 2021). "This is the first report on the generation of CD47scFv-hinge-CD4TM-CD28-41BB-CD3ζ CAR-T cells, demonstrating the effectiveness of CD47-CAR-T cells in against cancer cells A549." (PMID 34189144, 2021). "Increased CD47 has also been reported in cancer cells as part of an immune clearance avoidance mechanism, specifically for macrophages, and an antitumor therapy has been proposed by blocking CD47." (PMID 34638556, 2021). "CD47 is expressed on both normal and cancer cells, and interacts with SIRPα expressed on macrophages to send a “don’t eat me” signal, thus avoiding phagocytosis by macrophages." (PMID 34178692, 2021). "PDCD1, CD47 and CD94 inhibit the killing of cancer cells and are associated with B lymphocytes in many types of tumors." (PMID 33588924, 2021). "Immunotherapy specifically interrupting CD47/SIRPα communication, namely, anti-CD47 monoclonal antibody Hu5F9-G4, is currently under six clinical trials and has emerged as a breakthrough in cancer treatment for solid and hematological tumors." (PMID 34205047, 2021). "As a transmembrane protein, the binding of CD47 to SIRPα ligand on phagocytes results in phagocytosis resistance and cancer cell immune escape." (PMID 34512146, 2021). "Here, we show that levels of CD47, which is known to mediate immune escape in cancer and virus-infected cells, are elevated in SARS-CoV-2-infected Caco-2 cells, Calu-3 cells, and air−liquid interface cultures of primary human bronchial epithelial cells." (PMID 34698067, 2021). "In summary, we demonstrate that NTP is able to modulate the immune checkpoint CD47 in 3D cancer spheroids and tumors." (PMID 33540720, 2021). "Treating CD44hi/CD24low cancer stem cells with the CD47 blocking antibody B6H12 suppressed asymmetric division, stem cell transcription factors including Klf4 cell growth, and induced executioner caspase-7 activity." (PMID 33925464, 2021). "In the current study, we identified that treatment of cancer cells with Gal-9 skewed the phagocytic balance towards a pro-phagocytic phenotype by both upregulating PS and downregulating the CD47 surface expression." (PMID 35052746, 2021). "Combining these negative signals culminates in a decrease in macrophage phagocytic capacity, which is why the overexpression of CD47 confers survival advantages to cancer cells." (PMID 34944878, 2021). "Agents blocking the CD47-specific pathway, including CD47-specific antibodies, are currently tested as therapy alone or in combination with other therapies in different cancer types." (PMID 34831455, 2021). "CD47, a cell surface molecule overexpressed by several cancer types that facilitates immune escape from macrophages, dendritic cells and natural killer cells, and its ligand SIRPα, have emerged as potential therapeutic targets." (PMID 34944850, 2021). "ALX148, which is a CD47 blocking protein, was well tolerated in combination with anticancer antibodies and conventional chemotherapy in patients with advanced cancers (NCT03013218)." (PMID 34235155, 2021). "Therapeutic targeting of the innate immune checkpoint CD47-SIRPα has been shown to promote the potential of neutrophils as cytotoxic cells in different solid tumor indications using different cancer-targeting antibodies." (PMID 34503071, 2021).